GDF15 (growth differentiation factor 15)
Diseases named in the same sentence as GDF15 in open-access papers (continued):
Sharing a sentence is not in itself a finding about the gene and the disease.
bladder cancer (continued). "Our previous studies indicated that GDF15 is deemed as an antitumor gene in the human bladder carcinoma cells and CAPE treatment induces the expression of GDF15 via the MAPK and/or AMPK signaling." (PMID 35884930, 2022). "Growth differentiation factor-15 (GDF15), a member of the TGF-β superfamily, affects tumor biology of certain cancers, but remains poorly understood in bladder cancer cells." (PMID 26249737, 2015). "In this review, we focus on describing the emerging evidence for GDF15, VEGF, TGF-β1, HSP90, HMGB1, and S100A9 as candidate biomarkers across renal and bladder cancers—highlighting their biological rationales, analytical performance characteristics, and prospective roles in clinical practice." (PMID 41009692, 2025). "On the other hand, using the human GDF15 reporter vector, results of reporter assays revealed that rhTGFβ treatments downregulated the reporter activity, while co-treatment with CAPE reversed such effect in bladder carcinoma HT1376 cells." (PMID 35884930, 2022). "However, the interactions among GDF15, CAPE, and TGFβ/Smads signaling in the human bladder carcinoma cells remain unexplored." (PMID 35884930, 2022). "Moreover, our early report demonstrated that GDF15 is the upstream gene of two antitumor genes, NDRG1 and maspin, in bladder carcinoma cells." (PMID 35884930, 2022). "al. showed three novel gene loci, i.e., GDF15, TMEFF2, and VIM, whose DNA methylation could be suitable for detecting bladder cancers in urine samples." (PMID 32046186, 2020). "Meanwhile, the results illustrated that GDF15 modulates epithelial-mesenchymal transition (EMT) markers NDRG1, and maspin to suppress the cellular proliferation, invasion, and growth of bladder carcinoma cells in vitro and in vivo, and is defined as an antitumor marker of bladder cancer." (PMID 35884930, 2022). "Moreover, the expression, function, and regulation of GDF15 in bladder cancer have not been fully elucidated." (PMID 26249737, 2015). "Interestingly, our study is the first report which revealed that GDF15 blocked the effect of TGFβ/Smad signaling on the maspin and NDRG1 expressions in bladder carcinoma cells although GDF15 did not affect the phosphorylation of Smad 2/3 and Smad 1/5 in bladder carcinoma cells." (PMID 35884930, 2022).
cognitive decline (19 papers, 2014 to 2026). "Growth differentiation factor 15 (GDF15) has been associated with cognitive decline in several neurodegenerative diseases and movement disorders, providing a rationale for its investigation in CD." (PMID 41908486, 2026). "Like DNAm GDF15, plasma GDF15 was associated with better cognition at age 75 and greater rates of cognitive decline in all cognitive domains." (PMID 41274863, 2025). "Growth differentiation factor 15 (GDF15) is a transforming growth factor β superfamily cytokine implicated in age-related disorders, inflammation and cognitive decline." (PMID 37891738, 2023). "Several studies have reported that increased GDF15 levels were associated with PD, cognitive decline, AD, and Lewy body dementia." (PMID 35068064, 2022). "MIC-1/GDF15 is secreted into the cerebrospinal fluid and increased levels of MIC-1/GDF15 are associated with a variety of diseases including cognitive decline." (PMID 28081177, 2017). "A recent study from our group revealed that serum Macrophage Inhibitory Cytokine—1 (MIC-1/GDF15) levels were associated with cognitive decline." (PMID 25867953, 2015). "Interestingly, previously, we found that serum GDF-15 was associated with physical inactivity and cognitive decline in a similar patient population." (PMID 41463319, 2025). "Additionally, serum levels of MIC-1/GDF15 independently predict all cause mortality and cognitive decline in aging populations." (PMID 24971956, 2014). "Higher MIC-1/GDF-15 blood levels have been associated with a variety of diseases and conditions including inflammation, cardiovascular disease, various types of cancer [e.g., prostate, colon, melanoma, pancreas] neurodegeneration and cognitive decline, and all-cause mortality." (PMID 29628937, 2018). "In this study, we aimed to evaluate the potential of serum GDF-15 as a screening marker for cognitive decline in patients undergoing hemodialysis." (PMID 38397960, 2024). "In this study, GDF-15 levels were observed to be elevated in the group of hemodialysis patients with cognitive decline." (PMID 38397960, 2024). "GDF15 acts as a growth factor as well as immunomodulator, and has been thought to be involved in cognitive decline." (PMID 36635686, 2023). "MIC-1/GDF15 serum levels have also been related to cognitive decline in the elderly; a recent study from our group identified a strong cross-sectional and prospective negative association between MIC-1/GDF15 serum levels and cognitive function." (PMID 25867953, 2015). "The cross-sectional nature of our study precludes the determination of whether GDF15 elevation precedes or follows cognitive decline." (PMID 39851417, 2025). "And a study suggested that the increase of GDF15 in peripheral blood may be a marker of white matter hyperintensities‐related cognitive decline." (PMID 35068064, 2022). "Considering the associations of GDF15 with an unhealthy lifestyle, cardiovascular risk factors, and various age-related chronic diseases, including CKD, cardiovascular disease, cancer, and even cognitive decline, GDF15 can be considered a marker of biological age." (PMID 32375259, 2020).
myocardial ischemia (19 papers, 2017 to 2024). A disorder of cardiac function caused by insufficient blood flow to the muscle tissue of the heart. "Reportedly, high blood levels of GDF-15 are associated with inflammatory conditions, which is the hallmark of myocardial ischemia, and especially cancer." (PMID 38707901, 2024). "Highly elevated GDF-15 levels are mostly linked to inflammation, myocardial ischemia, renal pathology, cancer, or age-related frailty." (PMID 38892211, 2024). "Elevated GDF-15 levels are associated with inflammatory conditions, myocardial ischemia, autoimmune diseases, and various cancer types." (PMID 39283723, 2024). "Highly elevated GDF-15 levels are mostly linked to pathological conditions including inflammation, myocardial ischemia, and notably cancer." (PMID 32508832, 2020). "More recently WAP was shown to be associated with growth differentiation factor 15 (GDF15) levels, which is expressed in inflammation and myocardial ischemia and linked with poor outcomes in HF." (PMID 38273315, 2024). "Elevated levels of GDF-15 are present in different human pathologic conditions, including inflammation, myocardial ischemia, and different cancer histologies, being often associated with tumor aggressiveness." (PMID 39283723, 2024). "GDF-15, a cytokine belonging to the transforming growth factor family, is overexpressed in stress and inflammatory conditions, such as myocardial ischemia, cardiac pressure overload conditions, and cancer." (PMID 37106424, 2023). "GDF15 is recognized as a stress response cytokine, with its expression heightened in response to diverse cellular stressors such as inflammation, hypoxia, tissue injuries, and myocardial ischemia." (PMID 39766300, 2024). "While GDF-15 is typically highly expressed in the placenta and prostate and scarcely in other tissues, its expression increases in conditions such as myocardial ischemia, atherosclerosis, and cardiac pressure overload, playing a protective role in the myocardium." (PMID 38435138, 2024). "GDF-15 is a divergent member of the transforming growth factor β superfamily, is a stress-responding cytokine whose expression levels respond to a variety of cellular stress signals, such as inflammation, hypoxia, tissue injuries and myocardial ischemia." (PMID 38643287, 2024). "Basically, GDF-15 levels have been shown to increase right from the subclinical stages of HF, an expression of the pathophysiological continuum involving local and systemic inflammation, oxidative stress, or myocardial ischemia." (PMID 36556311, 2022). "We first demonstrated our ability to predictably shift analyte response curves with the growth/differentiation factor-15 (GDF-15) protein, which is a biomarker for inflammation, myocardial ischemia, and cancer." (PMID 37443317, 2023). "Growth Differentiation Factor-15 (GDF-15; aka macrophage inhibitory factor-1) is highly expressed in the settings of heightened inflammation and myocardial ischemia, is a regulatory switch for inflammation, cellular apoptosis, and angiogenesis, and predicts all-cause mortality and CVD." (PMID 35342890, 2022).
Glucose intolerance (18 papers, 2012 to 2025). Glucose intolerance (GI) can be defined as dysglycemia that comprises both prediabetes and diabetes. "GDF15 deficiency promotes glucose intolerance as well as hepatic and adipose inflammation in old mice." (PMID 32691494, 2020). "The results of the adoptive transfer study suggest that GDF15 deficiency in macrophages is associated with exacerbation of glucose intolerance by an altered immune environment in white adipose tissue." (PMID 29674655, 2018). "HFD-fed Gdf15−/− mice displayed aggravated glucose intolerance compared to HFD-fed WT mice, with increased levels of SMAD3 and PAI-1 in the skeletal muscle." (PMID 39825925, 2025). "For example, GDF-15, a protein involved in inflammation and cell repair processes, is secreted in response to high blood glucose levels as a protective factor from glucose intolerance." (PMID 39337670, 2024). "It has been observed that the metabolic effects of pharmacological activation of peroxisome proliferator-activated receptor β/δ (PPARβ/δ) on glucose intolerance and fatty acid oxidation were mediated by GDF15 expression." (PMID 38725041, 2024). "Old Gdf15 KO mice exhibited glucose intolerance compared to age‐matched WT mice during intraperitoneal glucose tolerance tests." (PMID 32691494, 2020). "Furthermore, HFD-fed Gdf15−/− mice display aggravated glucose intolerance compared to HFD-fed WT mice." (PMID 39825925, 2025). "Additionally, reduced mitochondrial OXPHOS function in muscle improved systemic energy homeostasis and glucose intolerance via GDF15 secretion from muscle in mice." (PMID 29222479, 2017). "Gdf15−/− mice displayed glucose intolerance compared to WT mice and feeding these mice the HFD resulted in a significant worsening of glucose intolerance compared to WT mice fed the same diet." (PMID 39825925, 2025). "The Gdf15‐Hi BXD strains placed on a normal chow diet exhibited glucose intolerance and a lower respiratory exchange ratio (RER) compared with the Gdf15‐Lo strains." (PMID 32691494, 2020). "Together, these data suggest that FGF21 and GDF15 act synergistically to improve glucose homeostasis and insulin sensitivity in OPA1 BKO male mice, with their combined absence resulting in glucose intolerance and prevention of improvement in insulin sensitivity." (PMID 40897647, 2025). "In addition, GDF15-deficient macrophages polarized into an M1-like phenotype, and reintroduction of GDF15-null macrophages into HFD-fed mice in which macrophages are depleted with clodronate, results in glucose intolerance." (PMID 29674655, 2018). "Interestingly, the beneficial effects of the PPARβ/δ agonist GW501516 on glucose intolerance, FA oxidation, ER stress, inflammation, and AMPK activation in HFD-fed mice were abrogated by the injection of a GDF15-neutralizing antibody as well as in Gdf15-/- mice." (PMID 34445261, 2021). "Consistent with the data from the chow‐fed mice, the Gdf15‐Hi strain fed with a HFD developed more severe glucose intolerance without any changes in food intake compared with the Gdf15‐Lo strain, but the Gdf15‐Hi group also showed a similar RER compared with the Gdf15‐Lo group." (PMID 32691494, 2020).
depression (17 papers, 2017 to 2025). "These markers also demonstrated strong correlations with depression severity: GDF15 was positively associated, while TGF-β1 and GDF11 were negatively correlated." (PMID 40958792, 2025). "Correlation analysis revealed that serum TGF-β1 and GDF11 were negatively associated with depression severity, while GDF15 levels showed a positive correlation." (PMID 40958792, 2025). "And depression in later life is associated with elevated GDF-15 levels, monitoring the GDF-15 levels of older adults are crucial for future research into the relationship between nutrition and depression." (PMID 40365427, 2025). "In the present study, correlation analysis revealed a positive association between GDF15 levels and depression severity, consistent with previous findings." (PMID 40958792, 2025). "We conclude that plasma GDF15 concentrations are significantly associated with combined cognitive-frailty-and-depression status and, with cognitive frailty and depressive symptoms separately in old as well as young community-dwelling adults." (PMID 37715843, 2024). "In our study, BMI is similar between the three cognitive frailty-depression groups, but is associated with GDF15 concentrations in adjusted regression analyses." (PMID 37715843, 2024). "High GDF15 levels were significantly associated with both-cognitive-frailty-and-depression (adjusted β = 0.177 [0.044 – 0.310], p = 0.009), and with low GCF scores and high SDS scores." (PMID 37715843, 2024). "Although not all studies have implicated GDF15 as an independent inflammatory biomarker for late-life depression, late-life depression was linked to high GDF15 levels, which were further related to lower cognitive functioning in adults with depression." (PMID 37715843, 2024). "High circulating levels of GDF15 were significantly and independently associated with a greater risk of both cognitive frailty and depression in the whole sample as well as in older adults." (PMID 38337499, 2024). "The results demonstrated that T/E ratio and GDF15 were closely associated with severity of depression." (PMID 36635686, 2023). "We performed a Spearman correlation analysis to explore the possible link between GDF-15 serum levels and other independent risk factors of depression in male MDD patients." (PMID 34942914, 2021). "Late-life depression is associated with GDF-15, a marker of age-related biological changes." (PMID 40672452, 2025). "Therefore, we evaluated cross-sectional associations of plasma GDF15 with combined cognitive-frailty-and-depression in older (i.e. ≥ 55 years) and younger adults of the MARK-AGE study." (PMID 37715843, 2024). "Since increased inflammation and advanced age are associated with frailty, with a decline in brain and cognitive function and with depression, we hypothesized that GDF15 is associated with both cognitive frailty and depression." (PMID 37715843, 2024). "Importantly, these significant higher GDF15 concentrations and significant associations of high GDF15 with a higher likelihood for both-cognitive-frailty-and-depression are confirmed in older adults." (PMID 37715843, 2024). "In order to further demonstrate whether the altered serum GDF15 level could alert sex hormone imbalance in depressive subjects, we analyzed the associations between log-transformed T/E ratio and depression risk biomarkers across the strata of T/E ratio." (PMID 36635686, 2023). "Furthermore, we showed that high plasma GDF15 is significantly associated with cognitive frailty and depression separately, where the associations with both conditions might be independent of age, BMI, sex, comorbidities and hsCRP." (PMID 37715843, 2024). "The final regression model was expressed by the equation: Depression severity = 29.260 − 1.254* TGF−β1− 0.032* GDF11 + 0.02* GDF15." (PMID 40958792, 2025).